CD34 (CD34 molecule)
Diseases named in the same sentence as CD34 in open-access papers (continued):
Sharing a sentence is not in itself a finding about the gene and the disease.
breast carcinoma (continued). "Moreover, individual CSCs in SCC (CD44+CD34+ITGA6+), lung cancer (ASCL1+/CGRP+ neuroendocrine cell) and breast cancer (CD44+CD24-, GSE124887) show concurrent activation of stemness genes, nuclear factors and mitochondrial components." (PMID 37463926, 2023). "As examples, CD34+ blasts and HER2+ breast cancer cells are arguably more challenging to score than CD138+ plasma cells, because these may show incomplete staining of tumor cells at variable intensities." (PMID 35242448, 2022). "Besides, western blot and immunohistochemistry assays indicated that RLT-03 significantly inhibited the expression of VEGF, EGF, CD34, IL-10, and TGF-β related to the angiogenesis and inflammatory regulation of breast cancer." (PMID 32595723, 2020). "Our data showed a significant decrease of Mfsd2a protein expression in vascular endothelial cells within brain metastases originating from primary breast cancer, lung cancer, and NEPC patient samples, as revealed by double immunofluorescence labeling with anti-Mfsd2a and anti-CD34 antibodies." (PMID 29844613, 2018). "By using a human blood-brain barrier in vitro model recently developed, consisting in CD34+ derived endothelial cells co-cultivated with pericytes, we show that ST6GALNAC5 expression decreased the interactions between the breast cancer cells and the human blood-brain barrier." (PMID 27529215, 2016). "Therefore, the aim of the present study is to examine the stromal expression of CD34 and SMA in lymph node and liver metastases which are two of the most frequent metastatic breast cancer sites." (PMID 25339428, 2014). "The objective of this study was to evaluate angiogenesis according to CD34 antigen expression in estrogen receptor (ER)-positive and negative breast carcinomas." (PMID 17718911, 2007). "Thus, microvessels in formalin-fixed paraffin-embedded specimens from 174 primary breast cancers were immunohistochemically stained with monoclonal antibodies to FVIIIRAg, CD31 and CD34 and ten fields counted at 200 x magnification for each antibody." (PMID 9376265, 1997). "Finally, the irregular structure of LVI led to a false-negative rate when we used D2-40 and CD34 for specific labeling of LVI in breast cancer." (PMID 38771398, 2024). "Excised xenografts were assessed histologically by H&E staining and immunohistochemistry for breast cancer marker (ERB1), proliferation marker (Ki67), mitotic marker (pHH3), hypoxia marker (HIF-2α), CSC markers (CD47, CD44, CD24, and CD133), and vascularization markers (CD31, CD34)." (PMID 34205080, 2021). "We therefore collected serum samples from healthy donors, breast cancer patients with primary tumors, and breast cancer patients with brain, bone or visceral metastases and analyzed its effects on human in vitro BBB model derived from CD34 + cells in co-culture with pericytes." (PMID 34915908, 2021). "Moreover, these AML cells could be enriched by using a combination of the cell surface markers CD34+CD38-2, while breast cancer-propagating cells were marked with CD44+CD24-/low3." (PMID 32754274, 2020). "Engraftment of CD34+ hHSCs in sublethally irradiated NOD/SCID/IL2rγKO (NSG) mice, previously shown to result in mature and functional human hematopoietic cells, was followed by intracranial implantation of the human brain-homing breast cancer cell line MDA-MB-231/brain." (PMID 31501884, 2020). "For example, miR-10a-5p as a vital modulator, could suppress the growth of chronic myeloid leukemia CD34+ cells, and miR-10b-5p targets the potent inflammatory mediator KLF4 (Kruppel-like factor 4) and has important roles in tumor invasion and the initiation of metastasis in breast cancer." (PMID 24223210, 2013). "Despite the fact that other morphological characteristics of the tumor vasculature are not available for evaluation, higher CD34-positive vascular structures might show a trend for the presence of immature vessels in basal-like breast cancers and TNBCs in this study." (PMID 22007214, 2012).
breast carcinoma (continued). "In tubular breast cancer and NST, CD34+ fibroblasts are absent in the intratumoral stroma, whereas, in ILC, these fibroblasts are present in approximately two thirds of the cases." (PMID 35205688, 2022). "In Cycle 0, in the absence of chemotherapy for the treatment of breast cancer, results showed that while PD response (ANC and CD34+) to a 6-mg dose of PF-06881894 was robust, the 3-mg dose was potentially subtherapeutic." (PMID 34618197, 2021).
melanoma (105 papers, 2001 to 2025). A malignant, usually aggressive tumor composed of atypical, neoplastic melanocytes. "The BRAFV600E mutations that were primarily found in melanomas also occur in brain tumors, which, similar to CD34, mainly affect low-grade glial or glioneuronal tumors, such as GG, DNT, and PA, as well as pediatric PXA and diffuse astrocytoma." (PMID 36307486, 2022). "Afterwards, they are stained for melanoma-associated chondroitin sulfate proteoglycan (MCSP) (melanoma cells), CD34 (endothelial cells) and CD45 (leukocytes) to differentiate between melanoma CTCs and other cells expressing MCAM." (PMID 35203714, 2022). "Here we generate a humanized (Hu)-mouse melanoma model by injecting fetal liver-derived CD34+ cells and implanting autologous thymus in immune-deficient NOD-scid IL2Rγnull (NSG) mice." (PMID 33436641, 2021). "For this, mice with 90–120 absolute CD8+ T-cell numbers/μl in peripheral blood were challenged with melanoma cells that are matched to one of the HLA-A allele expressed on the donor CD34+ cells." (PMID 33436641, 2021). "Linking epigenetics to tumor heterogeneity, upon exposure to targeted therapies, elevated KDM5B expression shifts melanoma cells to a more drug-tolerant CD34- state while KDM5B loss shifts melanoma cells to a more sensitive CD34+ state." (PMID 32042336, 2020). "Melanoma brain metastases were stained with anti-CD34 to assess vessel density and its association with edema." (PMID 31362777, 2019). "A lentiviral vector encoding HLA-A*0201-restricted TCR (DMF5 clone) specific for melanoma-associated antigen recognized by T cell-1 (MART-1) was used to engineer CD34+ FLCs." (PMID 26824989, 2016). "In the early phase, CD34 knockout mice with transplanted B16-F1 melanoma cells showed a decreased, and then later an increased tumor growth caused by a reduced capacity of CD34−/− hematopoietic cells." (PMID 24632811, 2014). "In xenografts tumor cell VM were associated with MECA32-positive mouse derived microvessels whereas in human melanoma metastases they associated and connected with CD34-positive blood vessels." (PMID 22442699, 2012). "LMS typically expresses smooth muscle markers (desmin, SMA) and lacks expression of CD117, DOG1, CD34, and S100, helping distinguish it from GISTs, sarcomatoid carcinomas, and melanomas." (PMID 41281033, 2025). "CD34+ hematopoietic stem cell–engrafted (HSC-engrafted) NOD-scid IL2Rgnull (NSG-GM3) mice were co-engrafted with syngeneic human melanoma tumors using the melanoma patient-derived xenograft (PDX) tumor model TM01149 (The Jackson Laboratory)." (PMID 40762981, 2025). "These macrophages have previously been shown to produce VEGF, and anti-VEGF therapy reduced melanoma growth to levels of non-CD34-engrafted MISTRG mice." (PMID 40503011, 2025). "The volume, weight and CD34 staining of the melanoma xenograft tumors increased by ROX were also attenuated by Vegfr2 silence." (PMID 39453043, 2024). "Literature reports on mice with spontaneous melanoma have shown that stem-like cells and CD34 tumor-initiating cells (TICs) depend on M2 macrophages for initiating tumor growth and determining specific tumor characteristics, including chemo-resistance." (PMID 37525217, 2023). "Briefly, NSG-SGM3-BLT mice were screened for human CD45+ cell engraftment at 8–10 weeks after CD34+ engraftment and inoculated subcutaneously with a human melanoma cell line." (PMID 37819238, 2023). "KDM5B upregulation following BRAFi treatment decreases H3K4me3 levels and triggers the conversion of melanoma cells from drug-sensitive CD34+ to drug-resistant CD34- cell states." (PMID 36497341, 2022). "We next determined site-specific differences in MVD between intracerebral and extracerebral melanoma metastases using anti-CD34 to identify endothelial cells." (PMID 32974852, 2021).
melanoma (continued). "Humanized MI(S)TRG mice given human CD34+ cells were xenografted with human melanoma cell line Me290 and demonstrated human macrophage infiltration into xenografted melanoma, more closely recapitulating a human TME53." (PMID 33659929, 2021). "Our observations on CD34+SCs/TCs in melanocytic nevi and malignant melanomas coincide with previous studies on the presence of CD34+ connective cells in melanocytic nevi and absence in melanomas." (PMID 34298962, 2021). "β-Elemene can also inhibit the growth of and metastasis of melanoma B16F10 cells through suppressing VEGF-mediated angiogenesis and the expression of CD34, a key marker of primary melanoma angiogenesis." (PMID 33801899, 2021). "The antiangiogenic effect was also confirmed by immunohistochemical analysis of tumors showing a reduced expression of the endothelial marker CD34 after oral administration of Curcuma zedoaria EO in C57BL/6 mice carrying B16-Bl6 melanoma." (PMID 32948083, 2020). "Human melanoma cell line A2058 was implanted into CD34+ huNOG mice, subcutaneously forming primary tumor and liver metastases." (PMID 32570871, 2020). "On IHC, tumour cells were positive for S-100 and vimentin, while negative for cytokeratin, epithelial membrane antigen (EMA), desmin, CD34, Melan-A, and human melanoma black (HMB-45)." (PMID 33520482, 2020). "In mouse melanomas, CD34+ and CD34- tumor subpopulations have been characterized as melanoma-propagating cells exhibiting some key properties from stem cell or progenitor cell." (PMID 32042336, 2020). "The in vivo effect of a-CTLA4-TGFβRII on Tregs was examined in human melanoma tumor-bearing NSG mice (NOD/Shi-scid IL-2rgnull) that were immune reconstituted with tumor-matched human leukocyte antigen (HLA) A2 + human CD34+ bone marrow (BM) cells." (PMID 29467463, 2018). "Tetramer+ T cells induced significant killing of HLA-A2+MART-1+ melanoma cells (Mel 624), providing further evidence that human T cells developing from the engineered CD34+ cells in hu-mice were functional." (PMID 26824989, 2016). "Melanoma metastases presented a highly complex neovascularization with immunoreactivity for CD34 and negativity for D2–40." (PMID 22442699, 2012). "Since both of these functions affect tumor development, we characterized the effect of CD34 ablation on tumor growth using the B16F1 melanoma model." (PMID 21494591, 2011). "Melanoma cells diverted the differentiation of CD34+ cells towards a dominant CD14+ population only if the progenitors were in an early growth phase." (PMID 11747338, 2001). "The pertinent negative markers include histiocytic markers (CD163, CD14, CD1a, langerin), FDC markers (CD21, CD23, CD35, clusterin, CXCL13), hematolymphoid markers (CD45, CD3, CD20, CD79a), vascular markers (CD31, CD34), melanoma markers (melanA, SOX10, HMB45, S100), and others (ALK, CD30)." (PMID 40563703, 2025). "It has been indicated that CD34-TICs induction through TAMs leads to melanoma development." (PMID 37525217, 2023). "Finally, we used DMEA to test data sets from human CD34+ cells treated with the glucocorticoid agonist dexamethasone and A2058 melanoma cells treated with the PI3K/mTOR inhibitor BEZ235." (PMID 37226094, 2023). "Current studies have determined that CD31 and CD34, being inexpensive and practical markers of vascular ECs, are significantly related to the evolution and prognosis of malignant tumors such as renal cell carcinoma and melanoma." (PMID 36185269, 2022). "Of course, it is possible that in melanoma patients other factors may interfere with DC maturation, including the prevalence of other DC populations, such as the plasmacytoid or the CD34+ derived DCs, as well as a disabled maturation of monocytes into DC." (PMID 33467521, 2021). "They found in mouse melanomas two cell subpopulations, CD34+ and CD34−, endowed with the characteristics of stem and progenitor cells, which may differ considerably in their clinical behaviors." (PMID 34575678, 2021).
melanoma (continued). "Data on sensitivity and specificity of the CellSearch platform based on immunofluorescence detection of HMW-MAA, CD45 and CD34 for patients with melanoma were reported in two patients only due to the decision of the company to not pursue further development of the technique." (PMID 34207653, 2021). "Beta-blockers, by decreasing the density of CD34+ fibroblasts may impair melanoma growth and slow down disease progression." (PMID 32353988, 2020). "As a-CTLA4-TGFβRII effectively counteracted tumor-infiltrating Tregs in vivo, we examined its ability to increase tumor-reactive IFNγ expression in T cells and inhibit tumor growth in human melanoma tumor-bearing NSG mice that were immune reconstituted with matched HLA A2+ human BM CD34+ cells." (PMID 29467463, 2018). "Additionally, we analyzed neovascularization in 49 primary melanomas and 175 melanoma metastases using immunostaining for blood (CD34) and lymphatic (D2–40) vessel-specific markers." (PMID 22442699, 2012). "Moreover, our previous studies also show that human resected melanoma brain metastases have lower CD34 + vessel density compared to matched extracranial metastases, but non-angiogenic vasculature has yet to be studied in specimens from patients with melanoma brain metastases." (PMID 38635031, 2024). "Interestingly, KDM5B overexpression reprogrammed melanoma cells to a CD34−, more drug-tolerant, phenotype, while KDM5B loss shifted melanoma cells to a more BRAFi-responsive CD34+ state, potentiating the pivotal role of KDM5A in modulating intratumoral heterogeneity in CM." (PMID 34575678, 2021). "The potential prognostic significance of LAT1 has been explored in melanoma patients, and the results indicated that high LAT1 expression is correlated with CD98, cell proliferation (Ki-67), and microvessel density (CD34) and with OS and disease-free survival." (PMID 40211360, 2025). "Immunohistochemically, the tumor cells were positive for S100 (5/6), cyclin D1 (2/3), SATB2 (2/3), BCOR (2/4), and TLE1 (1/3) while negative for MUC4 (0/6), keratin (0/5), EMA (0/4), desmin (0/6), CD34 (0/6), SMA (0/5), SOX10 (0/5), and pan melanoma (0/2)." (PMID 40705064, 2025). "Using the melanoma cell line, 624 MEL, as a control, we calculated the relative telomere length of the CD3+CD34+ cells transduced following each condition." (PMID 34172810, 2021). "As cancer stem cells (CSCs) are often associated with dormancy, slow growth, and drug tolerance, we measured the common melanoma CSCs biomarkers (CD271, CD44, CD34, and aldehyde dehydrogenase activity) to determine if the isolated persisters are CSCs." (PMID 34822435, 2021). "Gammelgaard and colleagues studied the growth and metastasis of human melanoma A375 cell line and two human triple-negative breast cancer (TNBC) cell lines, MDA-MB-231 and MDA-MB-468 in CD34+ HSC transplanted BRGS mice." (PMID 32570871, 2020). "In melanoma study, CD31 and CD34 expression have been shown to be related to trans-differentiation of melanoma cells, thus implying that immunoreactivity for CD31 and CD34 is closely parallel with tumor progression and aggressive behavior of tumor cells." (PMID 30833656, 2019). "The biopsy report showed metastasis of the melanoma with necrobiotic changes in the endothelium and vascular walls (CD31, CD34)." (PMID 29503781, 2017). "Von Willebrand factor, CD34, CD31, Ulex europaeus agglutinin 1, vascular endothelial growth factor, melanocytic markers (such as S100), human melanoma black-45, melanoma antigen and cytokeratins all are useful for diagnosis and differential diagnosis." (PMID 24067058, 2013). "Thus, a single marker may not be sufficient to isolate CSCs, and as a result, several markers are employed together to isolate certain types of CSCs, such as CD44+CD133+CD24+ cancer stem-like cells involved in murine melanoma, CD133+CD34+ melanoma CSCs, and CD133+/nestin+ lung cancer CSCs." (PMID 22558209, 2012).